IL37 (interleukin 37)
Diseases named in the same sentence as IL37 in open-access papers (continued):
Sharing a sentence is not in itself a finding about the gene and the disease.
colon carcinoma (continued). "In conclusion, the data showed that colon cancer cells expressed very low level of IL-37." (PMID 28467774, 2017). "Thus, we conducted the present retrospective study to investigate the effects of IL-37 (Interleukin 37), a newly identified anti-inflammatory factor, on colon cancer development." (PMID 28467774, 2017). "Zhang et al15 showed that IL‐37 might sensitize colon cancer to chemotherapy in mice." (PMID 30004182, 2018). "Therefore, we investigated the role of IL-37 in colon cancer in the current study." (PMID 28467774, 2017). "Furthermore, we also confirmed the anti-tumor effects of IL-37 in the mice model of colon cancer and demonstrated that IL-37 could sensitize the colon cancer cells to chemotherapeutic drugs." (PMID 28467774, 2017). "The anti-tumor effects of IL-37 in colon cancer development might be very complicated." (PMID 28467774, 2017). "However, whether IL-37 also shows anti-tumor effects in colon cancer remains unknown." (PMID 28467774, 2017). "Therefore, IL-37 might be a potential target for colon cancer treatment." (PMID 28467774, 2017). "Then the colon cancer cell line DLD1 and HT-29 were treated with different concentration of IL-37." (PMID 28467774, 2017). "The data showed that the IL-37 expression decreased at both mRNA and protein levels in colon cancer tissues comparing with its paired adjacent non-cancerous tissues, and this was further validated with western blot." (PMID 28467774, 2017). "Furthermore, the lack of IL-37 expression was showed as an independent prognostic marker for colon tumor recurrence." (PMID 28467774, 2017). "We found that the number of colonic tumors and the size of B16-OVA tumors in IL-37 absent and present mice when injected with IL-18-blocking antibodies was not significantly differences." (PMID 35046386, 2022).
psoriatic arthritis (10 papers, 2019 to 2026). Joint inflammation associated with psoriasis. "Ninety pediatric participants (JIA, CD, psoriatic arthritis, healthy controls) underwent serum cytokine profiling (IL-1α, IL-1β, IL-36α, IL-37, IL-6, IL-18, IL-27, IL-31) at baseline and 12 months." (PMID 42196228, 2026).
Hepatitis (9 papers, 2014 to 2023). Inflammation of the liver. "Alongside these prior studies, the present study added evidence for an IL-37-associated protective effect on MCMV-infected hepatitis." (PMID 37215069, 2023). "It has also been proposed that IL-37 can reduce Con-A-induced hepatitis by inhibiting the activity of DCs, blocking the biological effect of CD4+ T cells, increasing the proportion of Tregs and enhancing their function." (PMID 37215069, 2023). "The findings from the current study demonstrate the potential value of exogenous IL-37 in clinical management for HCMV-infected hepatitis." (PMID 37215069, 2023). "It has been reported that IL-37 is protective against hepatic ischemia/reperfusion injury, and IL-37 can affect concanavalin A (ConA)-induced hepatitis." (PMID 35419070, 2022). "In vivo expression of human IL-37 in mice reduces local and systemic inflammation in ConA-induced hepatitis and LPS challenge." (PMID 25960620, 2015). "The present study aimed to test a hypothesis on a protective role of IL-37 in CMV-induced hepatitis in a mouse model of acute murine CMV (MCMV) infection." (PMID 37215069, 2023). "The current study demonstrated that exogenous IL-37 might have played a protective role in MCMV-infected hepatitis, with reduced DCs and induced Tregs in MCMV-infected mice." (PMID 37215069, 2023). "The present study observed a protective effect of IL-37 on MCMV infected hepatitis, with significantly reduced serum transaminase levels in MCMV-infected mice by IL-37 pretreatment." (PMID 37215069, 2023). "The present study suggested that exogenous IL-37 can alleviate MCMV-infected hepatitis, likely through reduced DCs and induced Tregs with a weaker cytokine storm, demonstrating its potential value in clinical management for HCMV-infected hepatitis." (PMID 37215069, 2023).
melanoma (9 papers, 2017 to 2023). A malignant, usually aggressive tumor composed of atypical, neoplastic melanocytes. "The blood of melanoma patients contains lymphocytes (T, B, and natural killer cells) with increased IL-37 mRNA expression, with the highest expression in Treg cells." (PMID 34248996, 2021). "In addition, IL-37 is highly expressed in Treg of patients with melanoma and enhanced by melanoma secretome." (PMID 34084175, 2021). "IL-37 is expressed in diverse human tissues, such as skin, tonsil, placenta, breast, and melanoma." (PMID 28420941, 2017). "Similarly, Treg cells cultured in melanoma-conditioned media also express IL-37 mRNA and protein." (PMID 34248996, 2021). "In addition, the IL-1-mediated secretome from human melanoma cells, particularly TGF-β, induces IL-37 mRNA expression in human Treg cells." (PMID 34248996, 2021).
metabolic syndrome (9 papers, 2018 to 2023). A cluster of metabolic risk factors for CARDIOVASCULAR DISEASES and TYPE 2 DIABETES MELLITUS. "The use of recombinant IL‐37 for treatment in mice with metabolic syndrome was associated with improved insulin sensitivity and lower levels of pro‐inflammatory cytokines." (PMID 36757903, 2023).
myocardial ischemia (9 papers, 2016 to 2022). A disorder of cardiac function caused by insufficient blood flow to the muscle tissue of the heart. "IL-37 significantly alleviated ventricular remodeling after MI and myocardial ischemia/reperfusion injury in mice." (PMID 34471467, 2021). "Transgenic mice expressing human IL-37 (IL37-tg) mice exhibit a prominent protection from myocardial ischemia." (PMID 30728750, 2019). "We have previously demonstrated that IL-37 suppresses TLR-4 expression in murine myocardial ischemia/reperfusion injury." (PMID 31686988, 2019). "Correspondingly, an experiment in a mouse myocardial ischemia/reperfusion (I/R) injury model has further demonstrated that IL-37 exerts its anti-inflammatory effect via TLR-4/NF-κB inflammation pathway." (PMID 30728750, 2019). "IL-37 has been shown to attenuate inflammation in models of septic shock, chemical colitis, cardiac ischemia and contact dermatitis." (PMID 27863506, 2016). "Interestingly, our previous study with murine models showed that IL-37 alleviated cardiac remodeling and myocardial ischemia/reperfusion injury." (PMID 34471467, 2021). "The study also found that protective effect of IL-37 on myocardial ischemia-reperfusion injury was significantly reduced when IL-10 signaling pathway was blocked by a specific anti-IL10R mAb, indicating that the protective function of IL- 37 at least partially depends on the involvement of IL-10." (PMID 29805973, 2018). "Notably, in a mouse myocardial ischemia/reperfusion injury and MI model, we discovered that proinflammatory IL-6, IL-1β, and TNF-α were remarkably inhibited by IL-37 treatment, while IL-10, an anti-inflammatory cytokine, was significantly upregulated by IL-37." (PMID 34471467, 2021).
allergic disease (8 papers, 2014 to 2023). An immune response that occurs following re-exposure to an innocuous antigen, and that requires the presence of existing antibodies against that antigen. "However, we are at the point where IL-37 has been administered successfully in animal models of allergic diseases." (PMID 38067193, 2023). "Increased IL‐37 levels have been confirmed in numerous inflammatory and allergic diseases." (PMID 30414292, 2019). "The exact molecular and cellular mechanisms of the anti-inflammatory effect of IL-37 in the development of allergic diseases (AD) have not been fully studied." (PMID 31993235, 2019).
allergic rhinitis (8 papers, 2019 to 2025). Inflammation of the nasal mucous membranes caused by an IgE-mediated response to external allergens. "This inhibitory effect consequently reduces the proliferation, differentiation, and activation of Th2 cells, as observed in the IL-37-transgenic mouse model of allergic rhinitis." (PMID 39126010, 2024). "In an experimental murine model of allergic rhinitis, IL-37 administration led to decreased concentrations of IL-4 and IL-13 in serum and nasal lavage fluid, resulting in lower IgE levels." (PMID 39126010, 2024). "Future studies should explore whether SIGIRR contributes synergistically or independently to IL-37’s immunomodulatory effects in allergic rhinitis." (PMID 40427088, 2025). "IL-37 levels are decreased in conditions such as AD, asthma, and allergic rhinitis." (PMID 39126010, 2024). "In this study, we elucidate the negative role of IL-37 on the proliferation and function of Tfh2 cells in allergic rhinitis for the first time." (PMID 40427088, 2025).
coronary artery disease (8 papers, 2017 to 2024). "The present study aimed to evaluate the association of the IL-37 polymorphisms with premature coronary artery disease (pCAD), cardiovascular risk factors, metabolic parameters, and levels of liver enzymes." (PMID 34199391, 2021). "Moreover, IL-37 is highly expressed in human atherosclerotic plaque foam cells and elevated in patients with arterial calcification, indicating that IL-37 may be associate with the progression of coronary heart diseases." (PMID 34471467, 2021).
fibrosarcoma (8 papers, 2016 to 2022). A malignant mesenchymal fibroblastic neoplasm affecting the soft tissue and bone. "Recent studies indicate that IL-37 plays a protective role in tumor progression in mouse fibrosarcoma, human HCC and CC." (PMID 26791086, 2016).
inflammatory skin disease (8 papers, 2019 to 2024). Inflammatory skin disorders covers a broad category that includes many conditions ranging in severity, from mild itching to grave medical health complications These disorders are common in people of all ages and races. "In murine models, IL-37 has shown promise in suppressing inflammatory responses, suggesting the potential benefit of its modulation in treating inflammatory skin diseases." (PMID 39126010, 2024). "Further research is needed to explore the therapeutic potential of targeting IL-18 and IL-37 in inflammatory skin diseases, with ongoing and future studies likely to provide deeper insights and new treatment avenues." (PMID 39126010, 2024). "Recent studies have suggested that IL-33 and IL-37 are new potential therapeutic targets in inflammatory skin diseases." (PMID 37834081, 2023). "The role of IL-33/IL-37 interactions in inflammatory skin diseases has been reported." (PMID 37834081, 2023). "IL-37 also inhibits neutrophil migration and infiltration in inflammatory skin diseases." (PMID 36142901, 2022). "It thus remains to be determined if anti-inflammatory activity of IL-37 indeed contributes to human skin homeostasis in vivo or if treatment with recombinant IL-37 might be of therapeutic interest in specific inflammatory skin diseases." (PMID 33796114, 2021). "Thus, the upregulation of IL-37 in the skin may be an effective therapeutic approach to alleviate inflammatory skin diseases." (PMID 30918469, 2019). "The anti-inflammatory characteristics of IL-1Ra, IL-36Ra, IL-37, and IL-38, as well as their constitutive expression in keratinocytes, at the site of skin inflammation suggest that they could represent interesting therapeutic options for inflammatory skin diseases." (PMID 33796114, 2021).
lung adenocarcinoma (8 papers, 2019 to 2025). A carcinoma that arises from the lung and is characterized by the presence of malignant glandular epithelial cells. "It has been observed that decreased expression of IL-37 in human lung adenocarcinoma (LUAD) biopsies is associated with tumor metastasis." (PMID 36551790, 2022). "Intracellular mature IL-37 (amino acids 46-218) effectively inhibits the migration of multiple tumor cell types through the inhibition of Rac1 activation; thus, IL-37 loss or decreased expression in lung adenocarcinoma tissues results in tumor metastasis." (PMID 34248996, 2021). "Furthermore, reduced IL-37 expression in human lung adenocarcinoma biopsy samples is associated with tumor metastasis, indicating its potential crucial role in preventing the dissemination of tumors." (PMID 41293155, 2025). "Studies have demonstrated that exogenous IL-37 can induce apoptosis in human lung adenocarcinoma A549 cells, while inhibiting their proliferation, migration, and invasion." (PMID 41293155, 2025). "Elevated expression levels of IL-37 have been observed in lung adenocarcinoma (LUAD) tumors, and the expression profiles of both IL-37 and its receptor SIGIRR are correlated with LUAD development and tumor stage." (PMID 40444012, 2025). "The overexpression of IL-37 was able to increase the overall methylation of RNA m6A via inhibiting Wnt5a/5b pathway in lung adenocarcinoma A549 cells, thereby suppressing tumor proliferation." (PMID 37928545, 2023). "Our data revealed that amongst the 17 human malignancies investigated, IL-37 exhibits higher expression levels in tumors of lung adenocarcinoma (LUAD)." (PMID 36551790, 2022). "Towards that direction, our preliminary data support the fact that both IL-37 mRNA and protein are expressed by A549 human lung adenocarcinoma cells, as attested by a specifically developed RT-qPCR assay and flow cytometry." (PMID 36551790, 2022). "Since our initial results indicated that among various human malignancies, IL-37 exerts its highest expression in lung adenocarcinoma (LUAD), the study was subsequently focused on this cancer type." (PMID 36551790, 2022). "In this study, we found that the expression of IL-37 in lung adenocarcinoma tissue was significantly reduced compared to adjacent controls." (PMID 33489865, 2020). "We studied the m6A status of IL-37–treated human lung adenocarcinoma A549 cells and investigated the differences between the m6A modification patterns of untreated controls and the IL-37 treated model." (PMID 33489865, 2020). "The differential expression analysis of IL-37 between the lung adenocarcinoma and matched tumor normal tissues showed that the expression of IL-37 was lower in lung adenocarcinoma tissues than in adjacent, non-cancerous tissues." (PMID 33489865, 2020). "How IL-37 suppresses human lung adenocarcinoma growth is not completely understood." (PMID 33489865, 2020).
osteoarthritis (8 papers, 2017 to 2025). A noninflammatory degenerative joint disease occurring chiefly in older persons, characterized by degeneration of the articular cartilage, hypertrophy of bone at the margins and changes in the synovial membrane. "The results of this study will support the notion that targeting inflammation by blocking IL-33 and increasing IL-37 in osteoarthritis will attenuate cartilage loss." (PMID 35565085, 2022). "IL-37 expression is remarkably increased in synovial fluid of patients with synovitis compared with its expression in patients with osteoarthritis and disc displacement, and it is associated with the visual analogue scale score." (PMID 34248996, 2021). "While IL-36, IL-37, and IL-38 have been broadly investigated in both osteoarthritis (OA) and RA, this review examines IL-37 and IL-38 in RA more specifically, highlighting their emerging roles and therapeutic promise." (PMID 40777036, 2025). "IL‐37 was expressed in the synovium and the disc of patients with osteoarthritis (OA) and in the articular cartilage of condylar fracture patients." (PMID 31560411, 2019). "Here, we provide a detailed analysis of IL-37expression in EIOA and PGOA patients, and reveal the inhibiting effect of IL-37 in synovial inflammation of osteoarthritis." (PMID 28912428, 2017). "In this study, we investigated whether interleukin (IL)-37 ameliorates experimental osteoarthritis (OA)." (PMID 40970517, 2025). "Furthermore, decreased proteoglycan loss in human OA cartilage with IL-37 via inhibition of MMP-3 expression and the protection of stem cells in an inflammatory osteoarthritis-like microenvironment for cartilage formation support IL-33 and IL-37 as potential therapeutics." (PMID 34842603, 2021).
type 2 diabetes (8 papers, 2019 to 2025). "At the preclinical stage, as dose-effect responses have emerged in the current research on IL-37 in type 2 diabetes, it is crucial to comprehensively evaluate the dose-response relationship and safety of recombinant IL-37 under various pathological conditions in the future." (PMID 41293155, 2025).
allergic asthma (7 papers, 2017 to 2023). A asthma with a basis in a pathological type I hypersensitivity reaction. "In a mouse model of experimental allergic asthma, local application of recombinant IL-37 lowered the secretion of IL-4, IL-5, and IL-13, thereby reducing Th2-mediated allergic airway inflammation." (PMID 38067193, 2023). "IL-37 has been demonstrated to downregulate the proinflammatory activity of various innate immune cells, and it also inhibits allergic inflammation, as has been demonstrated by the local application of recombinant human IL-37 to mice suffering from experimental allergic asthma." (PMID 37759430, 2023). "Furthermore, the suppression of IL-33 and induction of IL-37 could exert anti-inflammatory activity in allergic asthma." (PMID 33919784, 2021). "A non-allergic asthma group was also included in this study and patients with non-allergic asthma exhibited increased expression of IL-37 compared to those with allergic asthma." (PMID 29137646, 2017).
Behcet disease (7 papers, 2011 to 2022). A chronic, relapsing, multisystemic vasculitis characterized by mucocutaneous lesions, as well as articular, vascular, ocular and central nervous system manifestations. "Conversely, decreased circulating IL-37 abundance has been observed in some inflammatory diseases, such as Behçet’s disease and inflammatory bowel disease (ulcerative colitis and Crohn’s disease)." (PMID 34367169, 2021). "For example, in Behcet’s disease (BD), both mRNA and protein expression of IL-37 was significantly reduced in PBMCs from patients with active disease compared to non-diseased individuals." (PMID 29137646, 2017). "Meanwhile, decreased IL-37 expression was detected in patients with Vogt-Koyanagi-Harada disease, intervertebral disc degeneration, and Behçet's disease." (PMID 26435567, 2015).
Hypercholesterolemia (7 papers, 2017 to 2024). An increased concentration of cholesterol in the blood. "Recent studies have identified IL-37 polymorphisms, such as rs2708961, rs2723187, and rs2708947, which are associated with a decreased risk of hypercholesterolemia in the Mexican population." (PMID 39337246, 2024). "In a previous study by our group, an association of the IL-37 rs2708961 and rs2708947 polymorphisms with a low risk of hypercholesterolemia was reported." (PMID 34199391, 2021). "IL-37 rs2708961, rs2723187, and rs2708947 polymorphisms under codominant 1 model are related to low risk of hypercholesterolemia." (PMID 34248996, 2021). "The aim of the present study was to evaluate the association of the IL-37 polymorphisms with the presence of hypercholesterolemia (HC), and with cardiovascular risk factors." (PMID 33028050, 2020). "Thus, the aim of the present study was to evaluate the association of the IL-37 polymorphisms with the presence of hypercholesterolemia, and with cardiovascular risk factors in a cohort of Mexican individuals." (PMID 33028050, 2020). "Some IL-37 polymorphisms have been associated with cardiometabolic factors in individuals with and without hypercholesterolemia." (PMID 39337246, 2024). "Nine IL-37 polymorphisms (rs2708965, rs2708962, rs6717710, rs2708961, rs2708960, rs2708958, rs2723187, rs2708947, and rs2723192) were determined by TaqMan assays in a group of 1292 individuals (514 with and 778 without hypercholesterolemia) belonging to the cohort of the GEA Mexican Study." (PMID 33028050, 2020).